MACC1 (MET transcriptional regulator MACC1)
Diseases named in the same sentence as MACC1 in open-access papers (continued):
Sharing a sentence is not in itself a finding about the gene and the disease.
non-small cell lung carcinoma (6 papers, 2012 to 2022). A group of at least three distinct histological types of lung cancer, including non-small cell squamous cell carcinoma, adenocarcinoma, and large cell carcinoma. "It has also been demonstrated that circFOXM1 can act as a sponge of miR-1304-5p such as to promote cell progression by regulating PPDPF and MACC1 in examinations of non-small-cell lung cancer-afflicted samples." (PMID 32904557, 2020). "However, the prognostic value of either MACC1 or ALDH1 in non-small cell lung cancer (NSCLC) is unclear." (PMID 27832750, 2016).
colorectal tumors (4 papers, 2012 to 2023). "We identified three different MACC1 SNPs and two Met variants in the colorectal tumors that are already annotated in the NCBI SNP database." (PMID 22838389, 2012). "We screened the coding exons of MACC1 for mutations and identified the MACC1 genotype cg (31 VL, rs4721888), ct (515 SL, rs975263) and gc or cc (804 RT or 804 TT, rs3735615) in a first panel of 60 colorectal tumors." (PMID 22838389, 2012). "In this study, we identified the SNPs rs4721888, rs975263, rs3735615 in the coding region of MACC1 in primary colorectal tumors." (PMID 22838389, 2012). "We analyzed the MACC1 mRNA expression in the set of 60 colorectal tumors." (PMID 22838389, 2012). "Furthermore, we studied the coding exons 14 to 19 of one of the transcriptional targets of MACC1, the proto-oncogene Met, in the first 60 colorectal tumors." (PMID 22838389, 2012). "Taken together, the analysis of the coding MACC1 variants 31 LV, 515 SL, 804 RT or 804 TT in primary colorectal tumors does not improve the prediction for metastasis formation or for patients’ survival compared to MACC1 expression analysis alone." (PMID 22838389, 2012). "We sequenced the coding exons of MACC1 in 154 colorectal tumors (stages I, II and III) and the crucial exons of Met in 60 colorectal tumors (stages I, II and III)." (PMID 22838389, 2012). "Expression of S100P and MACC1 correlated positively in CRC cells and colorectal tumours." (PMID 35597866, 2022). "In summary, the identification of coding MACC1 SNPs in primary colorectal tumors does not improve the prediction for metastasis formation or for patients’ survival compared to MACC1 expression analysis alone." (PMID 22838389, 2012).
cutaneous melanoma (4 papers, 2021 to 2024). A primary melanoma arising from atypical melanocytes in the skin. "In summary, our data suggest that MACC1 may be a potentially useful biomarker associated with progression of invasion and metastasis in cutaneous melanoma, especially in conjunction with high expression of MET protein." (PMID 37496665, 2023). "Specifically, MACC1 expression showed a statistically significant increase between primary and metastatic melanomas, suggesting MACC1 to be a more sensitive and reliable marker associated with metastasis in cutaneous melanomas." (PMID 37496665, 2023). "Recently, the prognostic value of MACC1 was demonstrated in cutaneous melanoma, showing higher levels of MACC1 expression in metastatic melanoma compared to primary melanoma." (PMID 39580452, 2024). "Here we demonstrate elevated level of MACC1 expression in cutaneous melanoma compared to benign melanocytic nevi, as seen in many other cancers." (PMID 37496665, 2023). "Our study suggests that high expression of MACC1 or both MACC1 and MET is associated with metastasis of cutaneous melanoma." (PMID 37496665, 2023). "However, there are limited studies in the current literature describing the expression of MACC1 in various stages of cutaneous melanoma in patient specimens or elucidating the role of MACC1 as well as its functional correlation with MET in tumorigenesis, progression, and metastasis of melanoma." (PMID 37496665, 2023). "In contrast, MACC1 expression was significantly lower in eight other types of cancer, namely adrenocortical carcinoma (ACC), HNSC, acute myeloid leukemia (LAML), LIHC, LUSC, pheochromocytoma and paraganglioma (PCPG), PRAD, and skin cutaneous melanoma (SKCM)." (PMID 36545127, 2022).
gastric adenocarcinoma (4 papers, 2016 to 2024). "Furthermore, in 2022 the prognostic value of MACC1 in esophageal and gastric adenocarcinomas was shown for the first time in a Caucasian patient cohort." (PMID 39580452, 2024). "However, the prognostic value of either MACC1 or KAI1 in gastric adenocarcinoma (GAC) is unclear." (PMID 27793161, 2016). "The effect of MEK1 inhibition has also been shown in the context of esophageal and gastric adenocarcinomas with the MEK1 inhibitor selumetinib, effectively reducing the migratory properties of cancer cells and metastasis formation in MACC1+ xenografted mouse models." (PMID 39580452, 2024).
gastric tumor (4 papers, 2019 to 2021). "MACC1 has been found to enhance gastric tumor cell migration, invasion and epithelial-mesenchymal transition (EMT) in vitro." (PMID 30805302, 2019). "Another lncRNA acting as a ceRNA that affects mRNA stability is MACC1 Antisense RNA 1 (MACC1-AS1), an intronic antisense lncRNA located between the fourth and fifth exon of MACC1, a transcriptional regulator of epithelial-mesenchymal transition (EMT) that enhances gastric tumor progression." (PMID 33466464, 2021). "The correlation analysis between expression levels of MACC1, c‐Met, and PDL1 and the clinicopathological parameters of gastric tumors found that the high MACC1, c‐Met, and PDL1 expression levels were associated with metastasis, tumor node metastasis stage, and life span." (PMID 31557409, 2019).
prostate carcinoma (4 papers, 2017 to 2024). A carcinoma that arises from epithelial cells of the prostate gland. "Thus, the roles and regulation of MACC1 in prostate cancer require further investigation." (PMID 38396744, 2024). "Surprisingly, no literature was found focusing on MACC1 in prostate cancer, the second most common cancer in males, pointing to the necessity of exploring the role of MACC1 in this entity." (PMID 39580452, 2024).
bladder cancer (3 papers, 2022 to 2025). "The GSEA results also indicated that low expression of the MACC1, GRB10 and MARCKS genes, along with high expression of the NINJ2 gene, were associated with tumourigenesis, including breast, pancreatic and bladder cancers." (PMID 39926275, 2025).
breast tumor (3 papers, 2013 to 2021). "MACC1 expression level was firstly tested by Western blotting analysis in eight paired normal breast tissue and breast tumor specimens from the same patients." (PMID 23497677, 2013).
cholangiocarcinoma (3 papers, 2020 to 2023). A carcinoma that arises from the intrahepatic biliary tree (intrahepatic cholangiocarcinoma) or from the junction, or adjacent to the junction, of the right and left hepatic ducts (hilar cholangiocarcinoma). "A different study demonstrated that MACC1 promotes angiogenesis in cholangiocarcinoma by upregulating VEGFA expression." (PMID 33425885, 2020). "MACC1 induced VEGF-C/VEGF-D in gastric cancer, and VEGF-A in gastric cancer and cholangiocarcinomas." (PMID 35406521, 2022). "In OS, we observed that MACC1 depletion had a modest effect on VEGFA expression levels (data not shown), suggestive of a differential regulatory mechanism for MCCA1 between OS and cholangiocarcinoma." (PMID 33425885, 2020).
endometrial cancer (3 papers, 2021 to 2025). Primary or metastatic malignant neoplasm involving the endometrium (mucous membrane that lines the endometrial cavity). "Our findings reveal that knockdown of MACC1 results in a decline in the invasive capacity of endometrial cancer cells, potentially linked to MACC1’s function in cytoskeletal organization." (PMID 40354443, 2025). "Our study demonstrates that down-regulation of MACC1 significantly curtails the migration and invasion of endometrial cancer cells." (PMID 40354443, 2025). "In this study, we aimed to develop a prognostic model for endometrial cancer (EC) patients based on mitochondria-related genes (MRGs), and to investigate the role of MACC1 in EC." (PMID 40354443, 2025). "Additionally, although we conducted both in vivo and in vitro experiments, the precise molecular mechanism by which MACC1 promotes endometrial cancer progression remains to be fully elucidated." (PMID 40354443, 2025). "Furthermore, the reduction in tumor cell migration and invasion observed in our experiments aligns with MACC1’s established role as a metastasis-promoting factor, providing a mechanistic basis for its prognostic value in endometrial cancer." (PMID 40354443, 2025).
melanoma (3 papers, 2021 to 2024). A malignant, usually aggressive tumor composed of atypical, neoplastic melanocytes. "The stepwise increase in the expression of MACC1, in particular, among melanocytic nevi, primary and metastatic melanomas suggest a stronger association of MACC1 with melanoma progression and metastasis." (PMID 37496665, 2023). "Metastatic melanomas demonstrate significantly stronger expression of MACC1 than primary melanomas (p=0.032) and nevi (p=0.0003)." (PMID 37496665, 2023). "There is a stepwise increase in MACC1 expression in nevi, primary melanomas and metastatic melanomas, with an average score of 103, 125.9, and 159.0, respectively." (PMID 37496665, 2023). "The role of HGF/MET signaling and expression of MET in melanoma has been studied more extensively than MACC1." (PMID 37496665, 2023). "Specifically, MACC1 is relatively diffusely positive in a cytoplasmic staining pattern in the melanoma and in benign melanocytic cells, but with variable intensity." (PMID 37496665, 2023). "Studies on MACC1 expression and its functional roles in melanoma are sparse, despite the known mechanistic link between MACC1 and HGF/MET signaling and their critical roles in inducing metastasis." (PMID 37496665, 2023). "Prior studies demonstrated that knockdown of MACC1 significantly inhibited the proliferation, migration, and invasion capability of melanoma cells in vitro." (PMID 37496665, 2023). "The average score for MACC1 expression in melanoma is 138.8, ranging from 70 to 200, with a standard deviation of 35.3." (PMID 37496665, 2023). "We observed significantly higher levels of MACC1 expression on average in metastatic melanomas, comparing to primary melanomas and nevi." (PMID 37496665, 2023). "The MACC1 expression is significantly higher in melanomas than in nevi (p=0.005)." (PMID 37496665, 2023). "MACC1 expression is observed in both melanomas and benign nevi." (PMID 37496665, 2023). "This study suggests the potential values of MACC1 and MET as useful biomarkers and warrants further evaluation on larger number of melanoma cases." (PMID 37496665, 2023). "Given the mechanistic interaction between MACC1 and MET, it is logical to postulate roles of MACC1 in melanoma progression and metastasis." (PMID 37496665, 2023). "We observed intermediate to high cytoplasmic expression of MACC1 and low to intermediate expression of MET in both melanocytic nevi and melanomas." (PMID 37496665, 2023). "In this study, we examined the extent of MACC1 and MET protein expression by immunohistochemical staining in a tissue microarray constructed from twenty-three melanomas and ten melanocytic nevi." (PMID 37496665, 2023). "This pattern was also seen in a few (38%) primary melanoma cases, however, the correlation between the expression scores of MACC1 and MET is stronger in the metastatic melanomas than in primary melanomas." (PMID 37496665, 2023). "While there is a trend in higher MACC1 expression in primary melanomas compared with benign nevi, this difference does not reach statistical significance (p=0.17)." (PMID 37496665, 2023). "It has been postulated that the interaction between MACC1 and MET signaling may be one of the mechanisms contributing to progression and metastasis of melanoma and other malignancies." (PMID 37496665, 2023). "The increasing trends of the average MACC1 and MET expression scores may suggest their role in melanoma development, progression and metastasis." (PMID 37496665, 2023). "Similar to MACC1, MET expression in melanomas is significantly higher than in nevi (p=0.018)." (PMID 37496665, 2023). "In the present study, we aim to investigate MACC1 and MET protein expression in melanocytic nevi, primary and metastatic human melanoma samples using immunohistochemistry, and further evaluating the prognostic value of MACC1 and MET, as well as their potential as biomarkers in melanoma." (PMID 37496665, 2023).
melanoma (continued). "The expressions of MACC1 and MET do not show significant differences based on patient age, gender, histologic subtypes of the primary melanoma, depth of invasion, and staging." (PMID 37496665, 2023). "MACC1 expression does not appear to correlate with MET expression in nevi and primary melanomas." (PMID 37496665, 2023).
metastasis (3 papers, 2013 to 2025). The spread or migration of cancer cells from one part of the body (where they first appeared) to another. "The association between MACC1 and lymphatic metastasis after stratifing age (N = 297)." (PMID 34343214, 2021). "At the same time, the probability of lymphatic metastasis was obviously increased even after adjusting all variables when MACC1 level higher than 1.4 (OR 11.2, 95% CI 1.5–81.5; p = 0.017) in the middle age group." (PMID 34343214, 2021). "We found both unadjusted and adjusted data showed a significantly positive correlation between MACC1 levels and lymphatic metastasis." (PMID 34343214, 2021). "Furthermore, the positive detection rates of MACC1 and AGR2 exhibited a positive correlation with tumor grade, tumor-node metastasis classification, and lymph node metastasis (LNM) stage, while demonstrating a negative correlation with OS." (PMID 41239615, 2025).
metastatic tumor (3 papers, 2013 to 2023). "This suggests that the association of MACC1 overexpression with presence of metastatic disease may be independent of the genetic features of CRC." (PMID 25884643, 2015). "MACC1 is overexpressed in malignant, especially metastatic tumors, but not in benign or non-metastatic tumor entities." (PMID 37627117, 2023). "Therefore, MACC1 is mainly expressed in highly malignant and metastatic tumors, without notable expression in benign tumors." (PMID 37627117, 2023).
rectal cancer (3 papers, 2012 to 2022). A primary or metastatic malignant neoplasm that affects the rectum. "We analyzed the diagnostic value of MACC1 levels for detection of tumors and metastases in colon and rectal cancer patients, and its prognostic value for overall survival (survival) of these patients." (PMID 23166620, 2012). "MACC1 levels were significantly higher in each disease stage of colon and rectal cancer compared with tumor-free volunteers." (PMID 23166620, 2012). "Rectal cancer patients characteristics and circulating MACC1 transcript levels in plasma." (PMID 23166620, 2012). "Diagnostic value of circulating MACC1 transcript levels in plasma of newly diagnosed colorectal, colon, and rectal cancer patients with a primary tumor with or without synchronous metastasis." (PMID 23166620, 2012). "Thus, MACC1 transcript levels in plasma supports the identification of individuals bearing colon and rectal cancer." (PMID 23166620, 2012).
squamous cell carcinoma (3 papers, 2020 to 2025). A carcinoma arising from squamous epithelial cells. "In addition, MACC1 was also shown to regulate the proliferation, apoptosis, migration, and invasion of squamous cell carcinoma cells via the induction of autophagy." (PMID 33425885, 2020). "Effect of KAI1, MACC1, and AGR2 on postoperative survival time in patients with squamous cell carcinoma of the uterine cervix." (PMID 41239615, 2025).
benign ovarian tumor (2 papers, 2011 to 2017). "Levels of VM, ALDH1, and MACC1 were significantly higher, and levels of KiSS-1 significantly lower, in EOC tissues than in benign ovary tumors." (PMID 28253891, 2017).
cervical squamous cell carcinoma (2 papers, 2022 to 2025). A squamous cell carcinoma arising from the cervical epithelium. "In cervical squamous cell carcinoma, the detection rates of MACC1 and AGR2 were found to be significantly elevated, whereas the detection rate of KAI1 was notably reduced when compared to control tissues." (PMID 41239615, 2025). "Among 106 selected cases of cervical squamous cell carcinoma, MACC1 expression was positive in 26 of 41 cases younger than 60 years of age (26/41, 63.4%) and in 39 of 65 cases older than or equal to 60 years of age (39/65, 60.0%)." (PMID 41239615, 2025). "Our univariate survival analysis revealed that the OS duration of patients with MACC1-positive cervical squamous cell carcinoma was significantly shorter than that of their MACC1-negative counterparts." (PMID 41239615, 2025). "Despite their individual associations with metastasis and prognosis across different cancer types, the interactions among MACC1, AGR2, and KAI1 specifically in cervical squamous cell carcinoma remain poorly understood." (PMID 41239615, 2025). "The impact of KAI1, MACC1, and AGR2 gene expression on postoperative survival rates among patients with cervical squamous cell carcinoma was assessed using the Kaplan–Meier method for univariate survival analysis." (PMID 41239615, 2025). "Immunohistochemistry was used to detect the expression of MACC1, AGR2, and KAI1 in 106 cases of cervical squamous cell carcinoma." (PMID 41239615, 2025). "In line with findings regarding MACC1, patients diagnosed with AGR2-positive squamous cell carcinoma of the cervix exhibited significantly shorter OS times than those with AGR2-negative tumors." (PMID 41239615, 2025). "However, investigations into the expression levels of KAI1, MACC1, and AGR2 in cervical squamous cell carcinoma, the interrelations among these biomarkers, and their associations with clinicopathological factors remain sparse." (PMID 41239615, 2025). "Sixty-five of the 106 cases of squamous cell carcinoma of the cervix (65/106, 61.3%) were positive for MACC1, and 8 (8/106, 7.5%) of the corresponding non-tumor control tissues were positive for MACC1, P < .05." (PMID 41239615, 2025). "In this investigation, a multivariate COX regression survival analysis revealed that the positive expression of KAI1, MACC1, and AGR2, along with TNM stage and LNM stage, are independent prognostic indicators for survival in individuals diagnosed with cervical squamous cell carcinoma." (PMID 41239615, 2025). "Correlations between KAI1, MACC1, and AGR2 expression in cervical squamous cell carcinoma." (PMID 41239615, 2025). "MACC1, AGR2, and KAI1 may represent potential metastatic and prognostic biomarkers, as well as promising therapeutic targets for squamous cell carcinoma of the cervix." (PMID 41239615, 2025). "Additionally, multivariate analysis indicated that the positive expression of MACC1, AGR2, and KAI1, alongside tumor stage and LNM stage, could serve as independent prognostic indicators for OS in individuals diagnosed with cervical squamous cell carcinoma." (PMID 41239615, 2025). "Therefore, this study aimed to investigate the relationships between MACC1, AGR2, and KAI1 within the context of cervical squamous cell carcinoma, while also examining their correlations with clinicopathological features and overall survival (OS) outcomes in affected patients." (PMID 41239615, 2025).